CHCHD3 (coiled-coil-helix-coiled-coil-helix domain containing 3)
Description:
Component of the MICOS complex, a large protein complex of the mitochondrial inner membrane that plays crucial roles in the maintenance of crista junctions, inner membrane architecture, and formation of contact sites to the outer membrane. Plays an important role in the maintenance of the MICOS complex stability and the mitochondrial cristae morphology. Has also been shown to function as a transcription factor which binds to the BAG1 promoter and represses BAG1 transcription.
Synonyms: MIC19; MINOS3; FLJ20420; PPP1R22; MICOS19
Tractability: PROTAC: ubiquitination databases record sites on it; its protein half-life has been measured.
Gene: Protein-coding gene on chromosome 7 (132,784,449 to 133,082,250, reverse strand). Ensembl gene ENSG00000106554.
Subcellular location: Mitochondrion inner membrane; Cytoplasm; Nucleus; Mitochondrion
Subcellular location (Human Protein Atlas): Mitochondria
Pathways (Reactome):
Organelle biogenesis and maintenance: Cristae formation
Protein localization: Mitochondrial protein import
Gene Ontology:
Molecular function: phosphatase binding; protein binding; molecular adaptor activity
Biological process: cristae formation; inner mitochondrial membrane organization; mitochondrial fusion
Cellular component: cytoplasm; extracellular exosome; MIB complex; MICOS complex; mitochondrion; nucleus; SAM complex; mitochondrial crista junction; mitochondrial inner membrane
Genetic constraint (gnomAD): Loss-of-function variants: 14 observed, 25.19 expected, observed/expected ratio (o/e) 0.56, 90% interval 0.37 to 0.87. The upper end of that interval is the gene's LOEUF score, 0.87, which puts it in group 3 of 6, group 1 being the genes least tolerant of losing a copy. Missense variants: 212 observed, 232.35 expected, observed/expected ratio (o/e) 0.91, 90% interval 0.81 to 1.02. Synonymous variants: 73 observed, 83.5 expected, observed/expected ratio (o/e) 0.87, 90% interval 0.72 to 1.06.
Homologues: Orthologues: macaque CHCHD3 (99% identical), guinea pig CHCHD3 (92% identical), mouse Chchd3 (90% identical), dog CHCHD3 (88% identical), pig CHCHD3 (88% identical), rat Chchd3 (86% identical), tropical clawed frog chchd3 (64% identical), zebrafish chchd3a (55% identical), zebrafish chchd3b (41% identical), Caenorhabditis elegans chch-3 (19% identical). Paralogues in human: CHCHD6 (33% identical).
Diseases named in the same sentence as CHCHD3 in open-access papers:
CHCHD3 is named in the same sentence as 27 diseases in open-access papers, as found by Europe PMC text mining. Sharing a sentence is not in itself a finding about the gene and the disease. The quoted sentences say what the papers report.
Obesity (3 papers, 2011 to 2025). Accumulation of substantial excess body fat. "Meanwhile, lncRNA-p19461 may protect mitochondrial function through regulation of CHCHD3, accelerating fat oxidation and reducing the incidence rate of obesity." (PMID 39652216, 2025). "We speculate that p19461 may protect mitochondrial function through regulation of CHCHD3, accelerating fat oxidation and reducing the incidence rate of obesity." (PMID 27767123, 2016). "There are no reports about the association between CHCHD3 and phenotypes related to obesity/diabetes in humans and rodents." (PMID 21383979, 2011).
familial amyotrophic lateral sclerosis (1 paper, 2016). An instance of amyotrophic lateral sclerosis that is caused by an inherited modification of the individual's genome. "Altered levels of MIC19/CHCHD3 are found in disease models for familial amyotrophic lateral sclerosis and ischemia." (PMID 27479602, 2016).
heart failure (1 paper, 2023). Inability of the heart to pump blood at an adequate rate to meet tissue metabolic requirements. "Compromised contractile capacity, diminished sarcomeric F-Actin and Myosin accumulation, and mitochondrial dysfunction in Chchd3/6 KD Drosophila hearts are promising phenotypes that could contribute to early HLHS manifestations or heart failure complications later in life." (PMID 37404133, 2023). "We next sought to understand if Chchd3/6 has different temporal requirements for its effects on heart structure and function, since hearts of operated HLHS patients often develop reduced ejection fraction and heart failure, including the 11 H proband." (PMID 37404133, 2023).
neuroblastoma (1 paper, 2022). Neuroblastoma (NB) is the most common solid, extracranial childhood tumor. "Exposure of neuroblastoma cells to toxic Aβ1-42, the APP cleavage product, did not alter protein or mRNA levels of CHCHD6, mitofilin, or CHCHD3." (PMID 36104602, 2022).
prostate carcinoma (1 paper, 2025). A carcinoma that arises from epithelial cells of the prostate gland. "This translocation induced the expression of ferroptosis-related protein coiled-coil-helix-coiled-coil-helix domain containing 3, promoting ferroptosis in prostate cancer cells." (PMID 41594579, 2025).
tumor (6 papers, 2012 to 2026). "Single cell analysis also found that the CHCHD3 was significantly up-regulated in tumor cells." (PMID 41567494, 2026). "The experimental findings further reveal that the up-regulation of CHCHD3 in LIHC might be intimately linked to the decline in proliferation and migration capabilities of tumor cells." (PMID 41567494, 2026). "CHCHD3 also showed a significant positive correlation with the levels of Wnt and TGF-β signaling pathways associated with epithelial-to-mesenchymal transition, suggesting its importance in tumor cell migration." (PMID 41567494, 2026). "Bioinformatics analyses further suggested the significant positive correlation between CHCHD3 and DNA replication and cell cycle pathway levels in LIHC, which indicates its close relationship with tumor cell proliferation." (PMID 41567494, 2026). "In the TCGA datasets, BC tumor tissue showed elevated gene expression levels of IMMT, CHCHD6, CHCHD3, APOO, and MICOS10 as compared to normal tissue, while the APOOL level was decreased in tumor tissue as compared to normal tissue." (PMID 36899366, 2023).
CNS tumors (1 paper, 2024). "Six different ROS1 fusion partners have already been described in pediatric CNS tumors (+/−7% of pediatric CNS tumors): GOPC, ARCN1, CHCHD3, ZCCHC8, TPR and CEP85L." (PMID 39409964, 2024).
CHCHD3 also shares sentences with these, for which no sentence is quoted: cancer (3 papers); fatty liver (2); liver diseases (2); asthma (1); bladder cancers (1); Cognitive impairment (1); colorectal cancer (1); diabetes (1); Hepatic steatosis (1); Huntington disease (1); Hyperglycemia (1); inflammation (1); intracerebral hemorrhage (1); ischemia (1); ischemic stroke (1); liver fibrosis (1); metabolism disorder (1); non-alcoholic fatty liver disease (1); nonalcoholic steatohepatitis (1); type 2 diabetes (1).